KRAS (KRas proto-oncogene, GTPase)
Diseases named in the same sentence as KRAS in open-access papers (continued):
Sharing a sentence is not in itself a finding about the gene and the disease.
lung adenocarcinoma (continued). "We show that oncogenic KRAS induces TE RNA and cell-intrinsic interferon (IFN)-stimulated gene (ISG) signatures and that KRAB zinc finger (KZNF) genes are globally downregulated both in vitro and in mutant KRAS lung adenocarcinomas in vivo." (PMID 35858545, 2022). "Nuclear translocation of NRF2 due to loss of KEAP1 expression by biallelic inactivation of the gene via mutation, loss of heterozygosity or promoter methylation has been shown to frequently occur in KRAS mutant lung adenocarcinoma." (PMID 35626147, 2022). "In this study, we have assessed the LOH of KRAS in early-stage lung adenocarcinoma by analyzing DNA copy number profiles and have investigated the effect on patient outcome in association with mRNA expression and somatic hotspot mutations." (PMID 35574381, 2022). "Actually, targeting GFPT2 by azaserine and targeting PGM3 by FR054 can specifically inhibit KRAS/LKB1 combined mutant lung adenocarcinoma cells, respectively." (PMID 36158580, 2022). "After culture in a defined small-molecule-based serum-free medium in a nonadhesive culture system, floating spheres with round and smooth contours were successfully obtained from A549 (EGFR wild-type, KRAS-G12S) human lung adenocarcinoma cells." (PMID 35956408, 2022). "We next sought to evaluate the potential for drug addiction in the context of treatment with AMG-510, the only KRAS-specific inhibitor currently approved for lung adenocarcinoma patients." (PMID 36418460, 2022). "Similar to sotorasib, adagrasib impairs cell viability of pancreatic and lung adenocarcinoma monolayer and spheroid models harboring KRAS G12C." (PMID 35251972, 2022). "KRAS is the most common oncogenic driver in LUAC, and STK11 alterations have been shown to confer primary resistance to PD-1 axis blockade in KRAS mutant lung adenocarcinomas." (PMID 36273184, 2022). "MEK inhibitors (MEKi) have limited efficacy in KRAS mutant lung adenocarcinoma (LUAD) patients, and this is attributed to both intrinsic and adaptive mechanisms of drug resistance." (PMID 36418460, 2022). "KRAS mutations are present in 30% of lung adenocarcinomas and lead to activation of the Ras-Raf-MEK-ERK signaling pathway, making it an attractive target for small molecule inhibition in KRAS mutant NSCLC." (PMID 36260870, 2022). "Common driver mutations (EGFR, ALK, BRAF, ERBB2, KRAS, MET, RET, and ROS1) analysis were performed in lung adenocarcinoma tissue samples from two PEAC patients (P08 and P10) using next-generation sequencing." (PMID 35172862, 2022). "This overview of the genomic and transcriptional landscape in lung adenocarcinoma stratified by LOH in KRAS suggests that the overall genomic and transcriptional landscape of lung adenocarcinoma is affected to some extent by the KRAS LOH status." (PMID 35574381, 2022). "For example, Song and co-workers observed lung-specific IKKα ablation in mince enhances KRAS-initiated lung adenocarcinoma development through a mechanism that regulates tumour cell-associated ROS metabolism." (PMID 35173303, 2022). "Blocking zDHHC20-mediated EGFR S-acylation has also been shown to reduce PI3K signaling and MYC levels and suppress cell growth in vitro and tumor growth in an in vivo model of KRAS-mutant lung adenocarcinoma." (PMID 36087837, 2022). "Mutated KRAS and EGFR are common oncogenic drivers of lung adenocarcinoma with predictive value for targeted therapies." (PMID 35627184, 2022). "Here, we present a rapid-autopsy case of a patient who had a KRASG12C-mutant lung adenocarcinoma who initially responded to a KRAS G12C inhibitor but then rapidly developed resistance." (PMID 34990404, 2022). "For example, Runx3 forms a complex with BRD2 in a KRas-dependent manner in the early stages of the cell cycle, resulting in the inactivation of Runx3 and promoting the development of lung adenocarcinoma." (PMID 36171897, 2022).
lung adenocarcinoma (continued). "To further study how KRAS and related oncogenes regulate alternative splicing, we performed a large-scale perturbation screen in A549 lung adenocarcinoma cells where the phenotypic readout is RNA sequencing." (PMID 36522653, 2022). "Nevertheless, recent studies have reported that KRAS mutant lung adenocarcinoma resistance to first-generation tyrosine kinase inhibitors (TKIs) is not due to downstream KRAS activation but rather to activation of other ErbB family members." (PMID 35319011, 2022). "Among KRAS-mutant lung adenocarcinoma, a particularly aggressive subset with STK11 comutations had higher repstress scores compared with tumors without comutations." (PMID 36381660, 2022). "Copy number changes in common hotspots in lung adenocarcinomas and associations between LOH in genetic hotspot regions and KRAS LOH." (PMID 35574381, 2022). "Mutations in the Kirsten rat sarcoma viral oncogene homolog (KRAS) gene are the most common alterations in non-small cell lung cancer (NSCLC); they are generally linked to smoking history and are typical of the lung adenocarcinoma (AC) subtype." (PMID 36077640, 2022). "In vivo and in vitro functional experiments confirmed that the ZNF24-SLC7A5 signaling axis promoted the proliferation, invasion and migration of KRAS mutant lung adenocarcinoma." (PMID 36505791, 2022). "According to the histological subtypes of NSCLC, lung adenocarcinoma (LUAD) and lung squamous carcinoma (LUSC) are associated with different mutational patterns, but are both mainly enriched for KRAS, EGFR, and ALK mutations." (PMID 36508072, 2022). "In previous work, we identified a specific mechanism in which the SMYD3-mediated methylation of MAP3K2 potentiates the oncogenic KRAS-driven pathway in lung adenocarcinomas." (PMID 35819319, 2022). "Key gene that regulated SLC7A5 in KRAS mutant lung adenocarcinoma was screened by RNA sequencing and bioinformatics analysis." (PMID 36505791, 2022). "For example, LKB1 mutation plays a key role in primary resistance to the PD-1 axis blockade in KRAS-mutant lung adenocarcinoma." (PMID 36074553, 2022). "In adenocarcinomas of the lung and related sputum and BALF samples, matched KRAS mutations have been found." (PMID 36552956, 2022). "Lung adenocarcinomas showing STK11/LKB1 defects, often in association with an altered KRAS, show poor response to immunotherapy." (PMID 36428727, 2022). "Co-mutation of KRAS and the tumor suppressor LKB1, one of the most prevalent mutational combinations in lung tumor, is observed in about ~25% of KRAS-mutant lung adenocarcinomas." (PMID 36074553, 2022). "KRAS G12C is the commonest KRAS mutation in NSCLC, seen in about 14% of all lung adenocarcinomas, followed by G12V." (PMID 36284306, 2022). "Our study indicates that LOH in KRAS is a prognostic factor that can refine the existing prognostic groups of lung adenocarcinomas." (PMID 35574381, 2022). "It was reported that STK11/LKB1 alterations as a genomic driver of primary resistance to PD-1 axis inhibitors in KRAS mutant lung adenocarcinomas." (PMID 36248982, 2022). "We aimed to explore the molecular mechanism and role in KRAS mutant lung adenocarcinoma progression." (PMID 36505791, 2022). "In particular, the highest frequency of KRAS alterations is identified in pancreatic adenocarcinoma (88%), colon and rectal adenocarcinoma (50%), and in lung adenocarcinoma (32%)." (PMID 35251972, 2022).
lung adenocarcinoma (continued). "These TE RNAs exhibit differential expression, are preferentially released in extracellular vesicles, and are regulated by KRAB zinc-finger (KZNF) genes, which are broadly downregulated in mutant KRAS cells and lung adenocarcinomas in vivo." (PMID 35858545, 2022). "KRAS mutations are among the most frequent genomic alterations identified in non-squamous non-small cell lung carcinomas (NS-NSCLC), notably in lung adenocarcinomas." (PMID 35406400, 2022). "Treatment with anti-SLC7A11 siRNAs induces significant cell death in KRAS-mutant lung adenocarcinoma cells." (PMID 35280777, 2022). "We previously identified an oncogenic activity of SMYD3 mediated by MAP3K2 methylation, promoting KRAS-driven lung adenocarcinoma tumorigenesis through ERK1/2 oncogenic activation." (PMID 35819319, 2022). "HDAC-10 deletion accelerates early-stage KRAS-driven lung adenocarcinoma, increases macrophage infiltration within the tumor microenvironment, and shortens the survival time in mice." (PMID 36263432, 2022). "EGFR, KRAS, and STK11 genes are known to be mutated in lung adenocarcinoma with a high frequency as well as ERBB2 with a lower frequency." (PMID 36499466, 2022). "Lung adenocarcinoma patients with LOH in KRAS had significantly better OS (HR = 0.65; 95% CI 0.45–0.95; p = 0.025) compared with patients with no KRAS LOH." (PMID 35574381, 2022). "With computed tomography of lung adenocarcinoma, it is already possible to link mutational status (EGFR, KRAS, and ALK) with imaging-assessed characteristics, such as lymphangitis, pleural effusion, or lung metastases." (PMID 35884409, 2022). "LKB1 inactivating mutations are observed in approximately 30% of patients with lung adenocarcinoma, and more frequently in those with KRAS mutant NSCLC." (PMID 33922215, 2021). "KRAS is the most frequently mutated RAS gene; KRAS mutations occur in 32–35% of lung adenocarcinomas (LUAD), 41–50% of colorectal adenocarcinomas (COAD), and 86–88% of pancreatic adenocarcinomas (PAAD)." (PMID 33924994, 2021). "Specifically, clinical studies have demonstrated that nonsense variants in STK11, which predict loss of STK11 function, correlate with primary resistance to PD-1 axis inhibitors in KRAS-mutant lung adenocarcinoma patients." (PMID 34849607, 2021). "It is important for SMARCA4 to be intact in oncogene-driven lung adenocarcinomas, as loss of SMARCA4 dampens the KRAS signaling in a KRAS-addicted cancer and, subsequently, impairs proliferation of the tumor cells." (PMID 34440689, 2021). "The relationship between lung adenocarcinoma subtype and lymph node involvement, EGFR mutation and KRAS mutation was also evaluated." (PMID 34026636, 2021). "For the Ras proteins, KRAS/HRAS/NRAS all harbor highly recurrent mutations for residues p.G12/G13 that affect large fractions of pancreatic adenocarcinoma (PAAD), COAD, READ, lung adenocarcinoma (LUAD), and UCEC." (PMID 33875650, 2021). "published a similar study, in which they use CRISPR/Cas9 mediated genome editing to identify LKB1 (STK11) tumor suppressing properties in KRAS-driven lung adenocarcinoma mouse models." (PMID 34781949, 2021). "Exploring the influence of wild-type (WT) KRAS on druggable targets can uncover new vulnerabilities for the treatment of KRAS mutant lung adenocarcinomas." (PMID 34573384, 2021). "In this study, we used a translational approach to characterize signal transduction events in homo- and heterozygous KRAS mutant lung adenocarcinomas with a focus on druggable targets and downstream substrates of FDA-approved or investigational agents." (PMID 34573384, 2021). "Understanding the underlying mechanisms of these changes can potentially uncover new druggable targets and fulfill the unmet therapeutic needs of patients with KRAS mutant lung adenocarcinoma." (PMID 34573384, 2021).
lung adenocarcinoma (continued). "Using commercially available KRAS mutant lung adenocarcinoma cell lines, we explored the influence of WT KRAS on signaling networks and druggable targets." (PMID 34573384, 2021). "In KRAS mutant pancreatic ductal adenocarcinoma and lung adenocarcinoma, for example, it has been demonstrated in cell lines that the dependence on RAS signalling varies tremendously." (PMID 34064232, 2021). "Last, another independent study used two genetically engineered mouse models of lung adenocarcinomas corresponding to the two most common oncogene drivers in human lung adenocarcinoma, KRAS and EGFR." (PMID 34631560, 2021). "DUSP6 was upregulated in EGFR- or KRAS-mutant lung adenocarcinoma cells with high ERK phosphorylation levels, which enables tumor cell growth by suppressing hyperactive ERK." (PMID 34685488, 2021). "To test the translational relevance of our findings in Drosophila we analyzed human lung adenocarcinoma genomic and clinical data using cBioPortal39,40 to study how differences in levels of oncogenic KRAS affect tumor progression in LKB1 mutant patients." (PMID 33514834, 2021). "It was recently demonstrated that NRF2 activation acts as a critical oncogenic driver, and can promote aggressive lung adenocarcinoma by cooperating with STK11 loss and KRAS activation." (PMID 33572782, 2021). "PIK3CA mutations can co-occur with activating mutations in RTKs such as EGFR, KRAS, and ALK in lung adenocarcinomas, as well as with the loss of PTEN in endometrial and breast cancer." (PMID 33809714, 2021). "Alterations involving ATM, and Cyclin Dependent Kinase Inhibitor 2A and 2B (CDKN2A and CDKN2B) have also been found in KRAS mutant lung adenocarcinomas." (PMID 34944952, 2021). "Oncogenes were detected in 64% of lung adenocarcinomas, while available information in relation to EGFR, BRAF, KRAS, ALK, ROS1, and MET gene mutations in lung adenocarcinomas are growing steadily." (PMID 34708154, 2021). "We evaluated the effects of fulvestrant and dacomitinib on murine bone marrow-derived macrophages (BMDMs) and CD8+ T cells, and tested the efficacy of the combination in vivo, using the KRAS mutant syngeneic lung adenocarcinoma model, FVBW-17." (PMID 35008514, 2021). "FKBP10 was also found to be upregulated in KRAS-mutant lung adenocarcinoma, renal cell carcinoma, and gastric cancer, and knockdown of FKBP10 is sufficient to hinder proliferation of tumor cells growth." (PMID 33557829, 2021). "Highly significant increases in both KRAS4A and KRAS4B transcripts were found in RNAseq data from KRAS mutant versus WT lung adenocarcinoma (LUAD) tumors, but KRAS4A showed a greater fold increase (1.7) than KRAS4B (1.2)." (PMID 34257283, 2021). "KRAS mutations are some of the most common drivers of NSCLC and are almost only detected in lung adenocarcinoma and rarely found in squamous cell carcinoma." (PMID 34012925, 2021). "KRAS mutations are one of the most common oncogenic drivers in non-small cell lung cancer (NSCLC) and in lung adenocarcinomas in particular." (PMID 34573384, 2021). "For instance, it was shown that the KRAS/MAPK/ERK/GLI1 activation could be mediated by either oncogenic KRAS mutation or stimulation of neuropilin 2 (NRP2) by vascular endothelial growth factor (VEGF) in lung adenocarcinoma (LAC) of non-small cell lung cancer (NSCLC)." (PMID 34572373, 2021). "Exploring the impact different genotypes can have on cell signaling events will help identify distinct druggable vulnerabilities and potentially advance precision medicine for KRAS mutant lung adenocarcinoma patients." (PMID 34573384, 2021). "All of them were downregulated in KRAS-mutant lung adenocarcinoma compared with normal lung tissues." (PMID 33435990, 2021).
lung adenocarcinoma (continued). "SDPR expression was evaluated by quantitative real-time PCR (RT-qPCR), immunohistochemistry (IHC), and Western blot on human NSCLC cells, lung adenocarcinoma tissue array, KRAS-mutant transgenic mice, TCGA and GEO datasets." (PMID 33435990, 2021). "Kirsten rat sarcoma viral oncogene homolog (KRAS) and EGFR are the most frequently mutated oncogenes in human lung adenocarcinoma." (PMID 34200786, 2021). "Meanwhile patients with KRAS mutations (KRAS+) had a better ICIs response rate, and STK11 mutation was found to be the main factor for PD-1 inhibitor resistance in lung adenocarcinoma with KRAS+." (PMID 33820866, 2021). "It has been reported that KRAS induced lung adenocarcinoma can activate the NF-κB pathway and promote tumor proliferation." (PMID 34475958, 2021). "Some mutations of common driver genes for lung adenocarcinoma also have been identified in BAs, such as EGFR, KRAS and BRAF." (PMID 34663408, 2021). "We also analyzed the isoform-specific expression levels of KRAS from TCGA lung adenocarcinoma (LUAD) samples." (PMID 34257283, 2021). "The KRAS gene had 181 and 180 driver mutations in colon adenocarcinoma (COAD) and lung adenocarcinoma (LUAD), respectively." (PMID 33179738, 2021). "Analysis of CDKN1A mRNA expression in 29 KRAS-mutant human lung adenocarcinoma cell lines revealed an inverse correlation with the previously published EMT gene signature." (PMID 34309585, 2021). "Lung adenocarcinoma, the most common histological subtype of non-small-cell lung cancer (NSCLC), often carries a KRAS mutation with 20–50% frequency, followed by squamous cell carcinoma, subtype of NSCLC." (PMID 33549031, 2021). "We further show that LKB1 mutant human lung adenocarcinoma patients with high levels of oncogenic KRAS exhibit worse overall survival and increased AMPK activation." (PMID 33514834, 2021). "In the analyses of oncogenic gene sets, we found six gene sets (SINGH KRAS Dependency Signature, CAMP UP.V1 UP, MYC UP.V1 UP, RB P107 DN.V1 UP, E2F1 UP.V1 UP and CSR LATE UP.V1 UP) associated with lung adenocarcinoma." (PMID 33446784, 2021). "This contrasts with human lung adenocarcinomas, in which mutant K-ras is thought of as oncogenic driver and of which between 19 and 33% were shown to harbor oncogenic KRAS mutations." (PMID 35295134, 2021). "The ERK-RAS Homolog Family Member A (RHOA) -FAK pathway is necessary to maintain KRAS-mutant lung adenocarcinoma." (PMID 34012925, 2021). "In preclinical models, KRAS G12C mutant lung adenocarcinoma cell lines treated with the ARS-1620 inhibitor displayed varying degrees of MAPK pathway reactivation." (PMID 34064232, 2021). "Findings show that KRAS-independent lung adenocarcinomas harbor higher rates of SMARCA4 inactivation as compared to KRAS-addicted lung adenocarcinomas." (PMID 34440689, 2021). "RET rearrangements are found in 1–2% lung adenocarcinoma and are mutually exclusive with mutations involving EGFR, ALK, ROS1, BRAF, or KRAS." (PMID 32448366, 2020).